CD24 (CD24 molecule)
Diseases named in the same sentence as CD24 in open-access papers (continued):
Sharing a sentence is not in itself a finding about the gene and the disease.
glioma (continued). "In our model, exogenous 2HG altered the expression of CD24 and CD44 in IDH-wt glioma cells." (PMID 40722659, 2025). "Additionally, Shikonin treatments resulted in diminished levels of glioma stem cell markers (SOX2, CD44, CHI3L1, and CD24) and the BMDM-derived TAM marker CD49D in glioma cells and subcutaneous animal models." (PMID 39619148, 2024). "Several CSC markers have been reported in glioma, such as CD133, CD24, CD90, CD44 and EpCAM." (PMID 30208924, 2018). "However, GFAP, SOX10, CD24, EMA, CKAE1/3, and PR negativity rule out meningiomas, glial tumors, schwannomas, metastatic melanomas or carcinomas." (PMID 41302074, 2025).
Sepsis (27 papers, 2014 to 2025). Sepsis is defined as life-threatening organ dysfunction caused by a dysregulated host response to infection. "In sepsis, CD24 associates with DAMPs, such as high-mobility group box 1, Hsp70, and Hsp90, negatively regulates their stimulatory activity and inhibits NF-κB activation through association with Siglec-G." (PMID 29209331, 2017). "Mice lacking Siglec-G were more susceptible to intestinal perforation-induced sepsis due to disruption of a Siglec-G/CD24 interaction, which leads to a failure in repressing host danger signaling-mediated inflammation." (PMID 24391502, 2014). "For instance, exosomes overexpressing CD24, combined with damage-associated molecular patterns (DAMPs), inhibit NF-κB pathway-mediated inflammation and have shown safety and efficacy in mouse models of lung diseases like sepsis, allergic asthma, COPD, and pulmonary fibrosis." (PMID 40496140, 2025). "Conversely, higher levels of IgD − CD24 − B cell % lymphocytes and CD86 on myeloid DC are associated with an increased risk of sepsis." (PMID 40797460, 2025). "This phenomenon mirrored those observed in sepsis models, where neuraminidase‐induced desialylation of CD24 disrupted its binding to Siglec‐G/10, leading to unchecked NF‐κB activation and systemic hyperinflammation." (PMID 40836885, 2025). "In our study, MR analysis showed that IgD+ CD24+ %B cells, CD45 on CD8br, SSC-A on HLA-DR + NK, and CD8br AC were reduced risk of sepsis, whereas SSC-A on plasmacytoid DC was increased risk of sepsis." (PMID 40909263, 2025). "In sepsis, the cross-linking of CD24 on the neutrophil surface is downregulated, resulting in delayed apoptosis." (PMID 38294676, 2024). "Conversely, higher expressions of CD24 and CD279 on neutrophils predict clinical worsening of sepsis, whereas lower expressions are associated with earlier discharge from the hospital." (PMID 38294676, 2024). "The CD24-Siglec-G interaction has been shown to be a crucial negative regulator of inflammation in sepsis." (PMID 33708213, 2021). "Some selected genes were significantly higher expressed in sepsis as compared with MBC samples (CD24, CD177, MMP8, and TLR5), and in MBC compared with sepsis (HLA-DRA, CSF1R, and AGAP6/9)." (PMID 32958605, 2020). "The molecule CD24 displayed reduced expression in cells from sepsis patients compared to those from healthy controls." (PMID 33111742, 2020). "The pathogenesis of sepsis involves multiple inflammatory mediators and a lot of them are regulated by the interaction of CD24 and Siglec-G." (PMID 29209331, 2017). "Using sialidase inhibitors to prevent disrupting sialic acid-based pattern recognition protected mice against cecal ligation and puncture (CLP) induced sepsis, and this process depended on the CD24 and Siglec-G interaction." (PMID 29209331, 2017). "It involves in the process of innate and adaptive immune response, and plays an anti-inflammatory role in sepsis through increasing IL-10 expression, interacting with CD24, inhibiting dendritic cell cross presentation, and weakening B cell signaling." (PMID 29209331, 2017). "Forest plots revealed that SSC-A on HLA DR+ NK, CD45 on CD8br, CD8br AC, and IgD+ CD24+ %B cell could reduce the risk of sepsis (IVW, b < 0), whereas SSC-A on plasmacytoid DC increase the risk of sepsis (IVW, b > 0)." (PMID 40909263, 2025). "CD24 was originally identified as involved in a series of inflammatory responses through binding with Siglec‐10 on innate immune cells, including in infection, sepsis, and liver damage." (PMID 41354057, 2025). "Using a cecal ligation and puncture (CLP) model to induce lethal sepsis in mice, investigators have suggested that bacterial sialidases may exacerbate sepsis through desialylation of CD24 and disruption of CD24/Siglec immunoregulatory pathway." (PMID 36294907, 2022).
Sepsis (continued). "In 26 upregulated OCRGs in AIs, the upregulation of two regulators, SERPINA1 and AZU1, was shared among acute respiratory distress syndrome (ARDS), sepsis, and trauma; upregulation of CD24 and FKBP8 was shared among ARDS and trauma; and upregulation of GRN was shared between sepsis and trauma." (PMID 34368262, 2021). "Peripheral blood transcriptomics in humans have shown a parallel scenario since particular key mediators of the initial neutrophil response to infection, such as LCN2, BPI, CD24, CASP1 and MMP8, were strongly dysregulated in patients with sepsis-associated ARDS compared to sepsis patients." (PMID 31426444, 2019). "Therefore, sialidase inhibitors targeting CD24-Siglec-G interaction has a great clinical potential in the treatment of sepsis." (PMID 29209331, 2017). "CD24 protects the host against the exaggerated inflammatory response in sepsis." (PMID 29209331, 2017). "Moreover, CD24 has been shown to be downregulated in the neutrophils of sepsis patients." (PMID 37553691, 2023). "Similarly, the Siglec-G’s interacting molecule CD24-/- mice showed increased mortality in sepsis." (PMID 33708213, 2021). "Among these molecules, CD24 and CD279 appear to be optimal biomarkers for predicting subsequent sepsis and worse outcomes." (PMID 38294676, 2024). "A multi-centre cohort study showed that lower mHLA-DR expression with increased neutrophil CD24 and neutrophil CD279 best predicted the clinical deterioration to sepsis." (PMID 36505404, 2022). "In this regard, the potential therapeutic use of CD24 in other conditions, where immune dysregulation plays a key pathophysiological role e.g., ARDS and sepsis, should be further exploited." (PMID 36294907, 2022). "Therefore, bacterial sialidases may exacerbate sepsis by CD24 desialylation." (PMID 33708213, 2021). "Treatment of CD24 protein with recombinant sialidases from three different bacteria, S. pneumoniae, C. perfringens, and V. cholerae dramatically reduced Siglec-G’s binding with CD24 and therefore exacerbated HMGB1 and HSP70 induced inflammation in sepsis." (PMID 33708213, 2021). "The CD24/Siglec 10 interaction has been investigated as a negative regulator of inflammation in sepsis, given that it inhibits Toll-like receptor (TLR) 4-induced cytokine production, and increases the regulatory interleukin (IL)-10." (PMID 36294907, 2022).
glioblastoma (24 papers, 2008 to 2026). The most malignant astrocytic tumor (WHO grade IV). "Bioinformatic analysis using UCSC genome browser reveals a CpG island between −828 to +430 bp, relative to the TSS and enhanced methylation of the Cd24 promoter has been associated with decreased expression in glioblastoma cells and diseased conjunctiva." (PMID 26301220, 2015). "The CD24/Siglec-10 interaction in context of malignant brain tumors has been scarcely studied.In silico analyses reveal that CD24 gene expression correlates with specific gene signatures associated with prognosis in both medulloblastoma and glioblastoma." (PMID 41606146, 2026). "Moreover, the overexpression of CD24 has been linked with worse outcomes following chemoradiotherapy in patients with glioblastoma and locally advanced HNSCC." (PMID 36013184, 2022). "Many studies reported that aggressiveness of Glioblastoma is linked with CD24 and ROS generation." (PMID 33473259, 2020). "Glioblastoma multiforme is associated with high expression of CD24 and ROS at basal level." (PMID 33473259, 2020). "The study discusses the prospects of using antibodies targeting CD47 or CD24 in the treatment of glioblastoma." (PMID 37900496, 2023). "For instance, antibodies against CD47 or CD24 have been proposed as new targets for glioblastoma therapy." (PMID 35822692, 2022). "The expression of CD24 is up‐regulated in glioblastoma stem cells and functionally involved in the migration, infiltration, and metastasis of glioblastoma cells." (PMID 34363319, 2021). "An overexpression of CD24 by more than two fold has been associated with poor overall survival in GBM, the poor survival may be related to increased “stemness” of tumor cells, which provides a potential therapeutic target for glioblastoma." (PMID 34363319, 2021). "This article reviews the feasibility of CD47/CD24 antibody treatment, either individually or in combination, to target the tumor stem cells and the antitumor immunity in glioblastoma." (PMID 34363319, 2021). "The immunotherapy resistance of glioblastoma to CD24 antibody treatment needs to be further investigated." (PMID 34363319, 2021). "From the translation perspective, the combined application of CD24 antibody with the CD47 antibody offers an additive effect against glioblastoma compared to either treatment alone." (PMID 34363319, 2021). "Whether CD47 or CD24 is directly involved in angiogenesis within glioblastoma is unknown, this should be investigated in future studies." (PMID 34363319, 2021). "Directly comparing glioblastoma and RRMS patients, higher fractions of CD5+ activated TZB (Bc 11) and CD24+/CD27+ Bregs (Bc 19) were noted in the PB of RRMS patients." (PMID 39497174, 2024). "Preclinical studies also investigated the potential of combining CD24 and CD47 for the treatment of glioblastoma." (PMID 37846296, 2023). "Concomitant manipulation of CD24 and CD47 has also been investigated as a potential treatment for glioblastoma in the preclinical setting." (PMID 36013184, 2022). "Notably, the expression level of CD24 was positively correlated with CD4+ T cell activation in MESO, LIHC, UCEC, glioblastoma multiform (GBM), LGG, and BRCA." (PMID 39791710, 2024). "Regarding the Bc and Pc compartment, RRMS and glioblastoma patients shared an increase in CD19+CD20− DN Bc, CD21− DN memory Bc, and Pc as well as a reduction in activated TZB while CD24+/CD27+ Bregs were only reduced in glioblastoma patients compared to controls." (PMID 39497174, 2024). "Nevertheless, given the importance of microenvironment, especially angiogenesis, in the prognosis of glioblastoma treatment, future immunotherapy against CD47 or CD24 should include the quantitative evaluations of hemodynamic changes within and surrounding the glioblastoma." (PMID 34363319, 2021).
glioblastoma (continued). "We further propose that the local application of the anti‐CD47/anti‐CD24 antibodies, combined with CAR‐T, tumor vaccines, immune checkpoint inhibitors, or other systemic immunotherapies will likely improve the overall efficacy for clinical treatment of glioblastoma." (PMID 34363319, 2021).
lymph node metastasis (23 papers, 2006 to 2025). "The membrane expression of CD24 has been reported to be associated with increased invasiveness, migration, and lymph node metastasis in gastric cancer." (PMID 40866457, 2025). "TNM stage, lymph node metastasis, and tumor size all had a strong correlation with the number of CD24-positive CTCs (p = 0.002, 0.020, and 0.025, respectively)." (PMID 38279998, 2024). "A total of 528 patients with CRC were included in four studies to evaluate the correlation between CD24 expression and lymph node metastasis, including 387 patients with invasion of the muscular layer and 78 patients without charge of the muscular layer." (PMID 35938128, 2022). "A total of 511 CRC patients were included in four studies to evaluate the correlation between CD24 expression and lymph node metastasis, including 198 patients with lymph node metastasis and 313 patients without lymph node metastasis." (PMID 35938128, 2022). "Correlation of CD24 positive expression with clinical-pathological features: age, sex, Duke’s stage, diameter, depth of invasion, degree of differentiation, and lymph node metastasis." (PMID 35938128, 2022). "In contrast, Soave and collaborators tested CD44 combined with CD24 in adenocarcinomas of the salivary glands, and found a strong correlation with tumour size and lymph node metastasis." (PMID 33009929, 2021). "Previous studies observed relationships between high CD24 expression and lymph node metastasis, venous invasion, and lymphatic invasion." (PMID 25212506, 2014). "The majority of the CD44+/CD24+ cases (66,6%) were classified as T3/T4 and the rate of positive lymph node metastasis was higher than the expected (35.7%)." (PMID 23419168, 2013). "CD24: correlation with the advanced stages, invasiveness, and lymph node metastasis of GC." (PMID 40777043, 2025). "CD24 has been reported as another marker for IMPC related to lymph node metastasis." (PMID 24708742, 2014). "Seven of 8 samples from lymph node metastases analyzed had the CD44+/CD24- phenotype." (PMID 24119896, 2013). "The results showed a significant correlation between the expression of CD24 in CRC and lymph node metastasis (RR = 1.90, 95% CI: 1.24–2.91, P = 0.003)." (PMID 35938128, 2022). "Simonetti's study demonstrated that IMPC had high expression of CD24 and low expression of CD44 compared with IDCs, which might explain the increased propensity for lymph node metastasis." (PMID 31839814, 2019). "The expression of CD24 in CRC was significantly correlated with a high-grade nuclear grade, lymph node metastasis, Duke’s stage, and age, but not with gender, tumor diameter, and depth of invasion." (PMID 35938128, 2022).
multiple sclerosis (22 papers, 2009 to 2025). A progressive autoimmune disorder affecting the central nervous system resulting in demyelination. "There are increasing studies focus on the association of a CD24 Ala/Val coding polymorphism with the susceptibility and progression of multiple sclerosis." (PMID 37359556, 2023). "Polymorphisms or deletions in the CD24 gene are associated with increased risk for autoimmune conditions, including lupus, giant cell arteritis and multiple sclerosis." (PMID 33915986, 2021). "Polymorphisms of the CD24 gene explored in the present study for their association with multiple sclerosis." (PMID 26039238, 2015). "Univariate meta-analysis for the 1527–1528 TG>del polymorphism of the CD24 gene with multiple sclerosis." (PMID 26039238, 2015). "Polymorphisms in CD24 have been associated with risk of immune-associated diseases such as multiple sclerosis, systemic lupus erythematosus, and irritable bowel syndrome." (PMID 26536476, 2015). "Univariate meta-analysis for the 1056 A>G and 1626 A>G polymorphisms of the CD24 gene with multiple sclerosis." (PMID 26039238, 2015). "Univariate meta-analysis for the 226 C>T (Ala57Val) polymorphism of the CD24 gene with multiple sclerosis." (PMID 26039238, 2015). "Two polymorphisms within the CD24 gene are known to modify disease risk and progression in multiple sclerosis (MS), systemic lupus erythematosus (SLE), giant cell arteritis, and in chronic hepatitis B." (PMID 21651777, 2011). "Tα1 treatment enhanced expansion of CD19+CD24+CD38hi transitional-immature and CD24low/negCD38hi plasmablast-like regulatory B cell subsets, thus inducing anti-inflammatory status and improving multiple sclerosis." (PMID 40599771, 2025). "Among these, the dinucleotide deletion of P1527 has the capacity to destabilize CD24 mRNA and, significantly, this deletion offers protection against both multiple sclerosis and SLE." (PMID 38313430, 2023). "Further evidence of a role for pDCs and IFN-α in the expansion of CD24+CD38hi Breg cells is provided by data reporting an enrichment of IL-10+CD24hiCD38hi B cells in multiple sclerosis (MS) patients responding to IFN-β therapy." (PMID 26968426, 2016). "CD24 was shown to be a co-stimulator to pathogenic CD4+ and CD8+ T-cell in various autoimmune conditions, including encephalomyelitis, thyroiditis, giant cell arteritis, multiple sclerosis and others." (PMID 33915986, 2021). "CD24 is a cell-surface protein mainly expressed in cells of the immune and central nervous system (CNS), cells that play a critical role in the development of multiple sclerosis (MS)." (PMID 26039238, 2015). "Literature showed that CD24 is required for the induction of experimental autoimmune encephalomyelitis (EAE), an experimental model for the human disease multiple sclerosis (MS)." (PMID 19173745, 2009). "In a multiple sclerosis (MS) mouse model (experimental autoimmune encephalomyelitis; EAE), CD24 expression on CNS resident lymphocytes facilitated disease development and increased the severity of the disease, whereas CD24 knockout mice were resistant to EAE induction." (PMID 33562144, 2021).
leukemia (18 papers, 2008 to 2025). A malignant (clonal) hematologic disorder, involving hematopoietic stem cells and characterized by the presence of primitive or atypical myeloid or lymphoid cells in the bone marrow and the blood. "Additionally, CD24 is a surface marker explored as a promising cancer immunotherapy target, and has also been linked to leukemia initiating cell (LICs) in KMT2A::AFF1 ALL." (PMID 40646135, 2025). "This is consistent with previous in vivo transplantation experiments, suggesting that CD24- leukemic granulocyte-monocyte progenitors (LGMPs) are more potent for inducing leukemia than CD24+ LGMPs." (PMID 25517911, 2014). "Herein we show that in leukemia cells ERG overexpression promotes a mesenchymal-like gene expression signature that includes: CD24, CD44, ITGA10, ITGB5, ITGB3, ITGA2B and the morphogenic-associated genes, such as SHANK3, TYROBP." (PMID 24504051, 2014). "We then stained MLL-AF9 primary leukemia bone marrow with antibodies against Flt3, lineage markers (Lin), Sca1, Kit, CD24, CD34, and CD16/CD32, and analyzed the samples by FACS." (PMID 25517911, 2014). "Notably, the PreProB subset, marked by surface CD24 expression, exhibits self-renewal capacity and reduced differentiation potential, suggesting a role as leukemia-initiating cells." (PMID 40646135, 2025). "In addition to solid tumors, CD24 has been identified as the most highly expressed immune checkpoint in leukemia stem cells (LSCs), and CD24+ multiple myeloma (MM) cells constitute a subtype of MM CSCs." (PMID 40486886, 2025). "Therefore, we FACS sorted subpopulations in the primary leukemia using Kit and CD24 markers as a proxy to the two leukemic cell subtypes, with the caveat that these two markers are insufficient to completely distinguish the two subtypes." (PMID 25517911, 2014). "Furthermore, ovarian and triple‐negative breast cancers that were particularly susceptible to CD24 blocking did not respond well to CD47‐blocking therapy, and vice versa in leukaemia." (PMID 33449453, 2021). "Anti-CD24 cross-linking antibody has been previously used to kill CD24-expressing leukemia cells, in vitro and in vivo, which raises the interestingly clinical implication that inactivating IRIS could sensitize TNBC cells, in vivo to an anti-CD24 cross-linking antibody therapy." (PMID 28052035, 2017). "In addition, Nfkb1-deficient leukemic cells presented a cell surface marker phenotype (expression of variable levels of CD4, CD8, CD24, CD25, and TCRβ/CD3ε) similar to that of Nfkb1-proficient cells (data not shown) and characteristic of transgenic TEL-JAK2 leukemia." (PMID 18596915, 2008).